CXCL2 (C-X-C motif chemokine ligand 2)
Diseases named in the same sentence as CXCL2 in open-access papers (continued):
Sharing a sentence is not in itself a finding about the gene and the disease.
infection (continued). "The NF-κB pathway is involved in the expression of several genes of the immune and inflammation response to the infection such as IFNβ, CXCL2 and TNF." (PMID 29084252, 2017). "The use of recombinant rabies viruses further indicates that this mechanism leads to the control of IFNβ, TNF and CXCL2 expression during the infection and a high pathogenicity profile in rabies virus infected mice." (PMID 29084252, 2017). "Inflammatory factors, such as TNFα and chemokines including Ccl2, Ccl5, Ccl9 and Cxcl2, were upregulated in response to more than one type of infection, particularly L. m and VSV." (PMID 28088779, 2017). "At 24 h, tonB K. pneumoniae infection also caused levels of induction of IL-6, CXCL1, CXCL2, IL-1β, and MIP-3α secretion that were comparable to those seen after 48 h of infection with WT K. pneumoniae." (PMID 27624128, 2016). "As expected, compared to uninfected controls, SA infection resulted in the increased expression of IL-1β, IL-6, and CXCL2 and their levels were significantly lower in Pam3 pretreated retinal tissue." (PMID 26865111, 2016). "Our systems biology analysis revealed that 13 hub genes, including the classical inflammatory genes (IL6, NFKB2, JUN, IL-1β, and CXCL2) which regulate retinal innate responses during infection." (PMID 26865111, 2016). "Our data shows that Cxcl2 was significantly upregulated on NTHi infection at 24 and 48 hpi, suggesting that our mMECs respond to bacterial infection in a manner similar to the native middle ear epithelium." (PMID 27660200, 2016). "Cxcl2 was significantly upregulated post-infection at 24 hpi (131-fold) and 48 hpi (36-fold) compared with the 24 hpi mock sample set as the reference." (PMID 27660200, 2016). "After infection with the clinical isolate, IL-1β and CXCL2, potent chemoattractants for neutrophils were both significantly reduced by GLY treatment." (PMID 27792814, 2016). "After infection of neonate mice by wild-typeSalmonella, a time-dependent increase in Cxcl2 and Cxcl5 mRNA expression was observed while mRNA expression was strongly reduced in enterocytes of adult mice isolated at day 4 after infection." (PMID 27408697, 2016). "Both CXCL1 and CXCL-2 expression decreased in Pam3CSK4-pretreated mice at 6 and 12 h post infection." (PMID 26974438, 2016). "We also studied expression of the pro-inflammatory chemokine Cxcl2 (MIP2α) during the progression of infection." (PMID 27660200, 2016). "Human chemokine C-X-C motif ligand 8 (CXCL8) or mouse functional homolog CXCL2, produced by immune cells, plays an important role in recruiting neutrophils to the sites of infection and inflammation." (PMID 26300888, 2015). "In line with our qRT-PCR data, we found that neutrophils in the infected WT brain were the predominant producers of Cxcl2 following infection, whereas Cxcl2 was undetectable in other tested cell populations." (PMID 26679537, 2015). "We found that both Cxcl1 and Cxcl2 were significantly induced following infection in both WT and Card9-/- mice whereas Cxcl5 was poorly induced." (PMID 26679537, 2015). "For example, the gene expression levels of the cytokines Cxcl1, Cxcl2, Cxcl5 and Cxcl17 was in agreement with the recruitment of neutrophils and DCs towards the site of infection." (PMID 25137043, 2014). "A. castellanii and A. culbertsoni but not A. castellanii Neff and A. astronyxis trophozoites induced significant CXCL2 production in Chinese hamster corneas 1, 3, and 7 days after infection." (PMID 24633052, 2014). "In this study, the expression levels of the genes encoding IL-8, CXCL2, and chemokine receptor CCR1 were upregulated during PCMV infection, suggesting that IL-8 exerts an effect similar to its effect during infection by other Herpesviridae family viruses." (PMID 25423176, 2014).
infection (continued). "The role of miR-146a in regulating NF-κB activation was consistent with the observed defect in downregulation of NF-κB-dependent cytokines and chemokines IL-1β, IL-6, Cxcl1 and Cxcl2, in B6 miR-146a−/− mice at 4 weeks post-infection." (PMID 24967703, 2014). "In the NOD-like receptor signalling pathway (hsa04621) 10 genes (of a total of 57 pathway genes) were differentially expressed at 4 h post infection and five of them were upregulated more than 10-fold, encoding IL6, IL1B, BIRC3, CXCL1 and CXCL2." (PMID 23326599, 2013). "Levels of IL-1β, CXCL-1 and CXCL-2 were higher in 5-LO−/− mice 24 h after infection compared with WT mice." (PMID 23991239, 2013). "The infection also activates the transcription of Cxcl1, Cxcl2 that regulate the influx of PMNs, Cxcl3 that controls migration of monocytes, Cxcl9 the Th1-attracting protein and the interferon-γ - inducible protein-10 (IP-10/Ccxl10)." (PMID 24148319, 2013). "Considering the concentration of IL-6 and CXCL-2, there was an increase of these mediators after 24 h of infection, and this increase was maintained after 72 h of infection compared to control animals." (PMID 23991239, 2013). "CXCL2 is important for neutrophil recruitment, and neutrophils are important for protection against infection with R. equi." (PMID 23690962, 2013). "The RV/NTHi group showed a significant reduction in chemokine levels of KC/CXCL1 and MIP-2/CXCL2 compared to the sham/NTHi group at 6 and 24 h post-NTHi infection." (PMID 23055935, 2012). "Of the chemokines, the functional murine IL-8 homologue KC/CXCL1 and MIP-2/CXCL2 were both markedly increased in CSF, brain homogenate and blood at 30 hours after infection." (PMID 22455545, 2012). "A time-dependent increase of the number of Cxcl-2+ and Cxcl-5+ epithelial cells was detected after infection with wt Listeria." (PMID 21124989, 2010). "Four hours after infection with 105 LSE, TLR2-deficient macrophages also demonstrated diminished production of IL-6, as well as the chemokines CXCL1 and CXCL2." (PMID 20404927, 2010). "In contrast, a strongly reduced number of epithelial cells stained positive for Cxcl-2 after infection with hly mutant Listeria." (PMID 21124989, 2010). "There was a good correlation between the levels of CXCL1 and CXCL2 in the lungs(B and FigS2A) and the recruitment of neutrophils after infection with 104and 106 PFU." (PMID 21079759, 2010). "Significantly (p≤0.01) elevated mRNA transcripts for both CXCL1 and CXCL2 were observed throughout infection compared to sham-infected control mice, and expression was independent of viral load." (PMID 20596532, 2010). "Both CXCL1 and CXCL2 were expressed at significantly higher levels after infection with HAdV-D53 than with HAdV-D22." (PMID 19492050, 2009). "The chemokine CXCL2 is involved in attraction of polymorphonuclear granulocytes to sites of infection." (PMID 17610738, 2007). "Moreover, an increased expression of macrophage inflammatory proteins (MIP1α, CCL3) and MIP2α (CXCL2) were found in bone samples of patients suffering from an infection of orthopedic prostheses." (PMID 40137369, 2025). "Quantitative RT-PCR analyses revealed peak expression levels of pro-inflammatory mediators such as TNF-α and CXCL2 in immune organs; however, CXCL2 expression in the spleen exhibited a slight decline during the late phase of severe infection, possibly reflecting viral immune evasion strategies." (PMID 41009378, 2025). "Besides analyzing ferroptosis-related protein markers, this cohort study also evaluated traditional biochemical indicators of infection, including IL-1β, IL-6, IL-8, IL-10, CXCL2, and TNF-α." (PMID 40264754, 2025). "We hypothesized that highly elevated expression levels of CXCL2 chemokine in the WT might be suppressing the expression of chemokine receptor on mononuclear cells during infection." (PMID 40977737, 2025).
infection (continued). "In contrast, inferred activity of this pathway increased starkly to become dominant in C3HeB/FeJ mice at 20 days after infection, driven by high predicted signaling activity of Cxcl2 between neutrophils, as well as from the macrophage/monocyte 1 and 2 clusters to neutrophils." (PMID 40986319, 2025). "Recruitment of neutrophils relies on their ability to sense and migrate towards chemoattractants, including the initial mobilization towards intermediate-target chemoattractants, like the chemokine CXCL2, and then end-target chemoattractants, like C5a and fMLP, to home to the site of infection." (PMID 39509414, 2024). "Neutrophils home to the site of infection through recognition of chemoattractant gradients, including intermediate-target chemoattractants, like the chemokine CXCL2, and end-target chemoattractants produced at the site of infection, such as complement product C5a." (PMID 39509414, 2024). "It is interesting that despite high infection levels of periodontopathic bacteria, the only inflammatory cytokines expressed in gingival tissue were IL-6 and CXCL2, which may reflect the “stealth” like properties of P. gingivalis as a keystone pathogens." (PMID 38233485, 2024). "Various chemokines (small proteins that guide white blood cells to sites of infection, injury, or inflammation) in this pathway, such as Cxcl1, Cxcl2, Cxcl3, and Cxcl5 and Ccl20, showed significant differences in expression levels between the LV149-L and the DSS group." (PMID 39845056, 2024). "Notably, our sequencing data revealed an upregulation of pro-inflammatory M1 macrophage markers, such as C-X-C motif chemokine ligand 2(CXCL2), in Tercko/ko mice following infection." (PMID 39607755, 2024). "Initially, intermediate-target chemoattractants, such as the chemokine CXCL2, guide the neutrophils in circulation to intravascular sites near the source of infection, where they can then bind to the activated vascular endothelium and extravasate into the tissue." (PMID 39509414, 2024). "Additionally, CCL3, CCL4, and CXCL2 levels were low at day 14 and recovered by day 28 post-infection, also in agreement with our findings." (PMID 39044282, 2024). "MdM-pat could release TNFA to upregulate CXCl2 expression in macrophages; this might be necessary for neutrophils to resolve the infection." (PMID 39298265, 2024). "Furthermore, tissue-resident macrophages can also express CXCL1, CXCL2, and various leukotrienes in response to infection." (PMID 38352492, 2024). "TNF-α has been shown to act as an innate helper factor produced by Ly6C macrophages+, whose function is to favor chemokines secretion (CXC motif) ligand 2 (CXCL2), responsible for the increase in the inflammatory response and neutrophile migration to the infection site." (PMID 39337365, 2024). "Mtb-induced CXCL1 and CXCL2 could play important roles in recruiting neutrophils to sites of infection and control the early infection." (PMID 36315280, 2023). "Similarly, Cxcl2 and Cxcl3 expression were increased during infection; however, there was a significant defect in TRPV1-/- mice to express these chemokines 29 days p.i. compared to WT mice." (PMID 38109366, 2023). "Interestingly, our results demonstrated that interaction scores of some paired ligands and receptors (e.g., ANXA1_FPR1, CD74_APP, CD74_COPA, CXCL1_CXCR1, CXCL2_CXCR2, and HLA-F_LILRB2) were significantly increased after infection." (PMID 37087411, 2023). "Notably, our results showed an upregulated transcriptional expression of cytokines (IL-1β, IL-6 and TNF-α), adhesion molecules (VCAM-1, ICAM-1) and chemokines (CXCL1 and CXCL2) after infection in both brain cortex and hippocampus." (PMID 36778380, 2023). "Notably, the NOD-like receptor proteins NOD1 and NOD2 can participate in innate immune responses, and NOD1 stimulates the release of chemokines, such as CXCL-8, CXCL-1, and CXCL-2, which can attract neutrophils to the site of infection." (PMID 35993024, 2022).
infection (continued). "Because we measured decreased levels of neutrophil chemokines CXCL1 and CXCL2, we hypothesized that immune cell recruitment to the lung in response to infection may be altered after fibrotic lung injury." (PMID 34990413, 2022). "Therefore, CXCL2 as well as other soluble mediators produced in the fibrotic lung before and after infection should be broadly evaluated and interrogated for their ability to drive or inhibit neutrophil antimicrobial responses." (PMID 36534439, 2022). "Based on our observation of decreased CXCL1 and CXCL2 in fibrotic lungs after infection, we hypothesized that immune cell recruitment to the lungs of these mice might be impaired." (PMID 34990413, 2022). "A number of non-infection associated genes that encode secreted proteins with potential to influence the phenotype of the infected cell and/or cells of the host immune system were also identified (e.g. IL9, CXCL2, CLEC3B and ADAMTS19)." (PMID 35061738, 2022). "In contrast, S100A9 and CXCL2 expressions were already highly induced in uninfected wounds of WT mice at day 2 as well as day 7, and these levels were much more highly increased by infection." (PMID 36275755, 2022). "Interestingly, Mmass infection significantly increased the TNF, IL-1β, and CXCL2 levels in BMDMs after 18 h of infection." (PMID 33473145, 2021). "Notably, both colonization levels and Cxcl2 mRNA levels were slightly higher following NB-cagA infection than following wild-type infection." (PMID 33837194, 2021). "Tracking the expression of this NF-κB gene signature across infection status reveals a pattern similar to Zeb2 and Cxcl2, suggesting that upon infection with Mtb, a subpopulation of AM_2 cells segregates within the IM_1 cluster, while others mount a pro-inflammatory response that is similar to IM_3." (PMID 34292313, 2021). "However, an enhanced upregulation of 9 genes, all involved in the NF-kB pathway (CCL2/MCP1, CCL20, CCL4, CXCL2/MIP2α, IL1A, NFKBIA, PTX3, TNFA, TNFAIP3), was observed after infection with D26 variants, in comparison to the WT." (PMID 33399033, 2021). "Neutrophil production of LTB4 and the release of another chemoattractant, chemokine CXCL2 (C-X-C motif chemokine ligand 2), is responsible for the collective coordinated behavior of neutrophils, called swarming, which is important for protection against severe pathogen infection." (PMID 35058789, 2021). "The role of polymorphonuclear cells during in-vivo WNV infection was investigated and discussed by Bai and colleagues, who observed that macrophages quickly express high levels of Cxcl1 and Cxcl2 upon infection, leading to the recruitment of polymorphonuclear cells." (PMID 34357089, 2021). "Indeed, the expression of CXCL1 and CXCL2, neutrophil-attracting chemokines, was significantly upregulated in macrophages upon infection." (PMID 34073501, 2021). "We found that the expression of CX3C subfamily (CX3CL1) and the C subfamily member (XCL1) was only highly increased in the H9N2-infected mice compared to the mock control, but the expression of CCL4, CXCL1, and CXCL2 was significantly increased in both single infection groups." (PMID 33968006, 2021). "What’s more, either SARS-CoV-2 or it’s variants infection, Meplazumab treatment had a favorable therapeutic effect on the downregulation of cytokines and chemokines at 6 d.p.i., such as IL-6, IL10, IL1b, CCL2, CXCL1, CXCL2, IFN-γ, IL-17, and CyPA." (PMID 34564690, 2021). "Previous study highlighted the role of Cxcl2 in promoting neutrophil infiltration during infection." (PMID 33664937, 2021). "Intriguingly, when looking at the infected cells, while Zeb2 is expressed by both clusters (AM_2 and IM_1), Cxcl2 is only expressed by IM_1, therefore indicating that subsets of cells in the AM_2 cluster may respond divergently to infection." (PMID 34292313, 2021).
infection (continued). "On the other hand, it is well established that CXCL8 induces chemotaxis in target cells, primarily neutrophils but also other granulocytes, causing them to migrate toward the site of infection while CXCL3 and CXCL2 controls migration and adhesion of neutrophils and monocytes." (PMID 32182886, 2020). "Interestingly, another CXCR2 agonist and neutrophil chemotactic mediator, CXCL2 were increased at 24 hr of infection in BAL fluid of ethanol-treated mice compared to control mice." (PMID 32701055, 2020). "However, in the present study, we observed high expression of CXCL2 in 1A0 and 6A4 female mice but these mice have shown to have the highest and lowest survival rate, respectively, post-infection." (PMID 32670284, 2020). "However, in response to infection, male mice exhibited higher expression levels of CXCL2 (KO, 1A3, and 6A2), SAMHD1 (1A0, 1A3), RSAD2, STAT1, and STAT3 (1A0), MYD88 and PSMB8 (1A3), BCL3, BCL10, CCRL2, IFITM2, RTP4, and ZFP36L1 (6A2), compared to females." (PMID 32670284, 2020). "Interestingly, in line with what we had observed in Gcnt1−/− infected mice, the expression of Cxcl2 upon infection was exclusively increased in Gcnt1−/−→Gcnt1−/− chimeric mice." (PMID 32203062, 2020). "Of interest, 1A3, and 6A2 males with high CXCL2 also showed low survival post-infection." (PMID 32670284, 2020). "CXCL1 and CXCL2 recruit neutrophils and other leukocytes to sites of infection and inflammation." (PMID 31848276, 2019). "By nanoString and real-time PCR profiling of the host response to the various mutants, we found that infection with the ΔgliP mutant enhanced expression of multiple chemokines, including CXCL2, CCL3, CCL4, and CCL7, which recruit neutrophils and macrophages to sites of inflammation." (PMID 30052103, 2018). "In addition, we saw no changes in tumor necrosis factor (TNF-α), IL-8, CXC chemokine ligand 2 (CXCL2), or IL-10 signaling in MRP1 knockdown cells either before or after infection as measured by an enzyme-linked immunosorbent assay (ELISA)." (PMID 29976647, 2018). "Accordingly, in the present study on day 40 both IFN-γ and Cxcl2 were unaffected by the infection." (PMID 28691023, 2017). "As the overwhelming neutrophilic inflammation and intense CXCL1 and CXCL2 production seemed to be associated with the severity of IAV infection, we wondered if antagonism of the receptors for CXCL1 and CXCL2 would impact the course of infection." (PMID 29326698, 2017). "Infection with WT K. pneumoniae induced significantly more IL-6 and CXCL2 than infection with the entB ybtS mutant, consistent with the siderophore-dependent effects observed and more IL-1β, which may be attributable to higher bacterial density." (PMID 27624128, 2016). "Interestingly, while JMJD3 was found to negatively regulate few of the mycobacteria-responsive M1 markers of macrophages viz., Il12, Il1b and Cxcl2, the expression of M2 markers like Arg1, Mrc1, Il10, Tgfb, Ccl17 and Ccl2 on infection were JMJD3-dependent." (PMID 27532872, 2016). "However by day 14 post challenge infection, CXCL2 was abundantly expressed, particularly at the lesion edge where it co-localized with FGFR1 expressing MF and F4/80 expressing MΦ." (PMID 25806513, 2015). "Furthermore, three recent studies have examined the role of TRPM2 channels in the CXCL2 production by immune cells in responses to infection and there were significant discrepancies in these studies using different cell preparations and infection stimuli." (PMID 26300888, 2015). "Together, our in vitro and in vivo data suggested, that MΦ, which populate the wound early after infection, might be activated by antibody-trapped helminth larvae to enhance MF recruitment to intestinal lesions by secreting CXCL2/3." (PMID 25806513, 2015). "Finally, we analyzed CXCL2 in Aid-/- mice that had received WT immune sera during challenge infection." (PMID 25806513, 2015).